CSF1R (colony stimulating factor 1 receptor)
Diseases named in the same sentence as CSF1R in open-access papers (continued):
Sharing a sentence is not in itself a finding about the gene and the disease.
Cognitive impairment (continued). "Unfortunately, it also appears that microglia are responsible for radiation-induced cognitive deficits and that elimination of microglia or CSF1R blockade reduces cognitive impairment and boosts radiation efficacy." (PMID 33187183, 2020). "We then screened CSF1R in an independent cohort composed of 465 mild cognitive impairment (MCI) and AD cases, identifying 2 additional mutations in CSF1R TK domain (p.Q691H and p.H703Y)." (PMID 29544907, 2018). "Our data demonstrate that elimination of microglia through CSF1R inhibition can ameliorate radiation-induced cognitive deficits in mice." (PMID 27516055, 2016). "The levels of CSF1R were correlated with cognitive impairment measured by MMSE and MoCA." (PMID 37108258, 2023). "Further studies are needed to determine if dendritic spine loss occurs at longer time points after brain irradiation, and whether temporary blockade of CSF-1R can permanently rescue this effect and ameliorate cognitive deficits." (PMID 27576527, 2016). "Mutations in colony-stimulating factor 1 receptor (CSF1R) are known to cause adult-onset leukoencephalopathy with axonal spheroids and pigmented glia (ALSP), which has been recently demonstrated as a primary microgliopathy characterized by cognitive impairment." (PMID 37259140, 2023). "Likewise, cognitive impairment is frequent in CSF1R-ALSP and occurs in 94% of cases." (PMID 37349768, 2023). "However, depletion of microglia by CSF-1R inhibitors in adult mice causes no noticeable cognitive deficits 17,18,22,23,29." (PMID 29777152, 2018). "In chronic unpredictable stress (CUS) models of cognitive impairment, increased CSF1/CSF1R activity drove microglial engulfment of neuronal components and spine loss in the medial prefrontal cortex (mPFC)." (PMID 41292555, 2025). "In contrast, effectively depleting CNS microglia by using PLX5622 (colony-stimulating factor 1 receptor [CSF1R] inhibitor) reduces hippocampal levels of inflammatory mediators and remarkably improves cognitive impairment." (PMID 36104739, 2022). "No behavioral or cognitive deficits were found in mice either depleted of microglia or treated with lower CSF1R inhibitor concentrations." (PMID 26232154, 2015). "In conclusion, these data suggest that using [11C]CPPC as a radioligand of CSF1R can detect microgliosis in early PD with at least moderate severity in patients, and that variance in [11C]CPPC binding within patients with PD correlates with disability from motor dysfunction and cognitive impairment." (PMID 40232849, 2025). "Moreover, quantifying CSF1R density with [11C]CPPC-PET imaging in living brains may provide an indicator of motor and cognitive impairments in the early stages of PD." (PMID 40519167, 2025). "Moreover, studies have indicated that high doses of another CSF1R inhibitor, PLX5622, can nearly eliminate microglial populations while improving learning and memory capabilities without causing cognitive deficits." (PMID 40153574, 2025).
lung carcinoma (30 papers, 2014 to 2026). "CSF1R was found to be differently mutated in many lung cancer patients affected explicitly by NSCLC and SCLC." (PMID 39201328, 2024). "It has been used to quantify colony-stimulating factor 1 receptor-expressing tumor-associated macrophages in lung cancer and programmed death ligand 1 expression in pancreatic ductal carcinoma." (PMID 37190293, 2023). "High expression levels of CSF1R were associated with high lung cancer-specific mortality (log-rank p = 0.037; hazard ratio (HR) = 1.61, 95% confidence interval (CI) = 1.02−2.52, p = 0.043)." (PMID 30065206, 2018). "In a Kaplan–Meier analysis, high expression levels of CSF1R were associated with higher lung cancer-specific mortality (5 years survival: 61 months) than low–moderate expression levels of CSF1R (5 years survival: 73 months; log-rank p = 0.037)." (PMID 30065206, 2018). "Other frequently mutated genes in the tumor tissue samples used in our lung cancer study were FLT3 (altered in 87% of the samples), KDR (84%), CSF1R (72%), PIK3CA (59%), and ERBB4 (53%)." (PMID 35330454, 2022). "In lung cancer treatment, preclinical study has suggested that CSF1R inhibition by BLZ945, a CSF1R inhibitor, substantially limits malignant pleural effusion formation induced by lung adenocarcinoma." (PMID 36439090, 2022). "Human patients with non–small cell lung cancer showed CD11c+ cell expansion with PD-L1 and CSF1R upregulation and decreased LAL expression in their blood." (PMID 35917184, 2022). "Tumor-bearing mice and human patients with non–small cell lung cancer also showed CD11c+ cell expansion with PD-L1 and CSF1R upregulation and immunosuppression." (PMID 35917184, 2022). "Again, high expression of CSF1R correlates with poor survival in lung cancer patients, similar with IL-34 and M-CSF expression." (PMID 29323162, 2018). "Similar with IL-34 and M-CSF, immunohistochemical staining showed that CSF1R is expressed in lung cancer tissues with a variety among patients." (PMID 29323162, 2018). "Here, the authors establish a platform for high-throughput 3D microscopy in murine lung carcinoma that allows to visualize TAMs infiltration throughout the entire lung, response to CSF-1R blockade and nanoparticle drug delivery." (PMID 28176769, 2017). "Furthermore, the group demonstrated that CSF-1R expression is necessary for chemoresistance in lung cancer." (PMID 38254773, 2024). "In lung cancer preclinical models, CSF-1R inhibition has been shown to sensitize cisplatin-resistant lung cancer cell populations against platinum-based therapy, further supporting its roles as an adjunctive agent not only to immunotherapy but also chemotherapy." (PMID 31439034, 2019). "As an exploratory analysis, we assessed the association of CSF1R expression with mortality in female patients, stratified by smoking status, because CSF1R SNPs have been associated with both risk of lung cancer and survival in never-smoking females." (PMID 30065206, 2018). "Evidence demonstrates that the expression and single nucleotide polymorphisms of CSF1R relate with survival and risk of lung cancer in never smokers." (PMID 30065206, 2018). "In never-smoking female patients, high expression levels of CSF1R were associated with high lung cancer-specific mortality (log-rank p = 0.010; univariable HR = 2.78, 95% CI = 1.22−6.32, p = 0.015)." (PMID 30065206, 2018). "First, we confirmed the expression of CSF1R on H358 lung cancer cells." (PMID 25313137, 2014). "Thus, we next evaluated the expression of CSF1R in lung cancer tissues." (PMID 29323162, 2018). "The association between high expression levels of CSF1R and lung cancer-specific mortality was stronger in never-smoking patients (log-rank p = 0.0027; HR = 2.90, 95% CI = 1.41−6.11, p = 0.0041) than in ever-smoking patients (log-rank p = 0.73; HR = 1.11, 95% CI = 0.59−2.00, p = 0.73)." (PMID 30065206, 2018). "In addition, overexpression of CSF-1R was related to chemotherapy resistance in lung cancer." (PMID 29228668, 2017).
lung carcinoma (continued). "Intervention of the CSF1/CSF1R and IL-6/IL-6R ligand-receptor pairs significantly reduced the ability of CHI3L1 lung cancer cells to recruit macrophages." (PMID 41362730, 2026). "These GO terms encompass six genes relevant to lung cancer found primarily in “Pathways in cancer” GO and partially overlapping with two other GOs: FLT3, FOXO1, CSF1R, RUNX1, PPARG, and TGFBR2." (PMID 39201328, 2024). "We use αCSF1R (anti-CSF1R antibody), PLX3397, and αIL-6 (anti-IL-6 antibody) to treat subcutaneous lung cancer as method described." (PMID 36969873, 2023). "Studies on animal models of lung cancer have now shown that MAF is highly expressed in TAM, where it controls the immunosuppressive polarization and function and the expression of the Csf1r gene." (PMID 36380627, 2023). "The study found that in the animal model of lung cancer, knocking out or blocking CSF1/CSF1R will significantly reduce the number of TAMs, proving that blocking the survival signal of macrophages was one of the effective ways to prevent and treat lung cancer." (PMID 37006240, 2023). "Immunohistochemical staining of IL-34, M-CSF, CSF1R and CD163 was performed on lung cancer tissues obtained from patients by surgical resection." (PMID 29323162, 2018). "Toceranib phosphate is also capable of blocking PDGFR, VEGFR, Flt-3, CSF1R, RET, ALK, and AXL, which may provide potential benefits for dogs with primary lung cancer." (PMID 39902337, 2024).
prostate carcinoma (29 papers, 2009 to 2025). A carcinoma that arises from epithelial cells of the prostate gland. "In prostate cancer, CSF1R activation enhances tumor-associated macrophage infiltration and contributes to resistance under androgen deprivation therapy, underscoring its potential as a therapeutic target in malignancy." (PMID 41313502, 2025). "The upregulation of CSF-1R expression was associated with macrophage growth in breast and prostate carcinomas." (PMID 29228668, 2017). "According to the study, low levels of CSF-1R and CSF-1 mRNA were detected in human prostate cancer cell lines, indicating the autocrine activation of the receptor." (PMID 38254773, 2024). "In summary, this study has demonstrated the functionality of CSF-1R in prostate cancer cells and has unveiled osteopontin as a CSF-1R-target gene." (PMID 36555673, 2022). "To determine if CSF-1R is also functional in human prostate cancer cells, we selected two malignant prostate cancer cell lines." (PMID 36555673, 2022). "Altogether, these data showed that CSF-1R expression in prostate cancer cells altered their potential in terms of growth, adherence, and invasion." (PMID 36555673, 2022). "Since all these biological properties play key roles in tumor development, this strongly suggests that CSF-1R has the ability to stimulate prostate cancer progression." (PMID 36555673, 2022). "Colony-stimulating factor-1 receptor (CSF-1R), a primary regulator of macrophage development, correlates with normal prostate growth and prostate cancer progression." (PMID 36117852, 2022). "Though, CSF-1R expression has been reported in mouse and human prostate cancer tissues and cell lines." (PMID 36555673, 2022). "Yet no study has been performed that specifically aimed at determining the biological effects of CSF-1R in prostate cancer cells." (PMID 36555673, 2022). "All together and in agreement with those obtained in murine cells, these results confirmed the functionality of CSF-1R in prostate cancer cells and osteopontin as a downstream target of CSF-1 signaling in these cells." (PMID 36555673, 2022). "Since CXCL12 is a classical ligand of CXCR4 and CSF-1/CSF-1R crosstalk from prostate cancer cells to recruited macrophages was previously identified, we proposed that the feedback crosstalk from macrophages to cancer cells is partly mediated by CXCL12/CXCR4." (PMID 34069563, 2021). "In summary, prostate cancers with increased Δ133TP53β mRNA were characterized by an immunosuppressive phenotype as illustrated by an increased frequency of PD-1, PD-L1 and CSF1R positive cells." (PMID 31431617, 2019). "The CSF-1R is expressed in normal intestinal and upper airway epithelia and lung, ovarian, breast and prostate cancers, or epithelial cell lines derived from them." (PMID 23451116, 2013). "Notably, this specific macrophage population expresses reduced levels of CSF1R transcripts, indicating a potential link to the clinical ineffectiveness of CSF1R blockade in prostate cancer treatment." (PMID 39633050, 2025). "Taken together, through single-cell assessment, our data enabled us to identify analogous Spp1hi-TAMs with elevated immunosuppressive gene signatures across multiple mouse models of prostate cancer, and we subsequently demonstrated their resistance to CSF1R inhibition." (PMID 39633050, 2025). "In the context of prostate cancer treatment, Sun’s silicic acid-bound CD/CSF-1R siRNA supermolecule nanoparticles can target the siglec-1 (CD169) overexpressed by M2 macrophages to obtain the up-regulated CSF-1/CSF-1R signaling pathway, which is related to poor prognosis of cancer patients." (PMID 37513483, 2023). "This suggested that some CSF-1R functions in macrophages were conserved in prostate cancer cells." (PMID 36555673, 2022). "Thus, signaling pathways downstream of CSF-1R in prostate cancer cells were similar to those in myelomonocytic cells." (PMID 36555673, 2022).
prostate carcinoma (continued). "Thus, OPN is one example of how prostate cancer cells, via the CSF-1/CSF-1R axis, are able to remodel the extracellular matrix and the immune landscape." (PMID 36555673, 2022). "Here we show that CSF-1R is functionally active in mouse and human prostate cancer cells." (PMID 36555673, 2022). "Few studies have investigated the expression of CSF-1R and its ligand in prostate cancer." (PMID 36555673, 2022). "Using a panel of the human prostate cancer tissue specimen, they showed by immunohistochemistry that CSF-1R is expressed by almost all specimens with the most intense signal in prostatic intraepithelial neoplasia (PIN) and carcinomas of histological Gleason grade three or four." (PMID 36555673, 2022). "Interestingly, analysing publicly available data of human prostate cancer revealed that CSF1R is expressed at higher levels in intermediate- and late-stage prostate cancers." (PMID 31417189, 2019). "Given that CSF-1R also plays a critical role in the tumor immune landscape, more research is warranted in this area for a better understanding of how CSF-1R regulates prostate cancer development and how this knowledge could be used in terms of therapeutic strategies." (PMID 36555673, 2022). "Therefore, this study has endeavored to establish whether CSF-1R is functional in prostate cancer cells." (PMID 36555673, 2022). "This prompted us to explore whether CSF-1R expression is functional in prostate cancer cells." (PMID 36555673, 2022). "Altogether, these results strongly suggest that CSF-1R is able to play an active role during prostate cancer development, which is in accordance with the previous studies demonstrating that CSF-1R expression is correlated with poor prognosis of prostate cancer." (PMID 36555673, 2022). "Consequently, we measured the number of CSF1R positive macrophages in the prostate cancers." (PMID 31431617, 2019). "Other CSF1R+ inhibitors include: the c-Fms inhibitor edicotinib (JNJ-40346527), in the treatment of prostate cancer (ClinicalTrials: NCT03177460); the kinase inhibitor vimseltinib, in the treatment of sarcomas, as well as TGCT (NCT04242238, NCT05059262)." (PMID 35158779, 2022). "Another CSF-1R inhibitor is edicotinib, which is used in prostate cancer therapy, without significant alterations in the CSF-1R+ immune cell population." (PMID 39457618, 2024). "Clinical studies in prostate cancer demonstrated that overexpression of colony-stimulating factor (CSF-1) and its receptor (CSF1R or c-FMS), were responsible for monocyte and macrophage expansion, indicating poor prognosis in primary prostate cancers and development of bone metastasis." (PMID 26459393, 2015). "Our laboratory has recently shown that targeting MDSCs using anti-CSF1R in combination with VTP therapy not only decreased the numbers of intratumoral MDSCs and TAMs, but also increased CD8+ T cell infiltration, decreasing tumor growth and improving overall survival in a prostate cancer model." (PMID 34205347, 2021). "Importantly, some CSF-1 or CSF-1R inhibitors are already available and are in clinical trials for the treatment of advanced carcinoma, e.g. LY3022855 (IMC-CS4) (NCT01346358, phase I: metastatic breast and prostate cancer); PLX 3397 (NCT01596751 phase Ib/II: metastatic breast cancer)." (PMID 26098772, 2015).
colorectal cancer (28 papers, 2013 to 2026). A primary or metastatic malignant neoplasm that affects the colon or rectum. "This illustrates that the loss of miR-34a in tumor cells and its repression by CSF1R could have an effect on therapeutic and prognostic measures of colorectal cancer." (PMID 38725047, 2024). "Preclinical studies in colorectal cancer have achieved increased anti-tumour efficacy with CSF1R inhibitory small molecule PX17 compared to AMG820." (PMID 41601679, 2026). "For instance, the blockade of CSF1R (using the monoclonal antibody AMG820) in combination with PD1 blocking antibody (Pembrolizumab) has been tested in clinical trials with colorectal cancer patients, although exhibiting a modest objective response rate of 6%." (PMID 41601679, 2026). "CSF1R is a novel identified dependence receptor; Ligand-free CSF1R exerts anti-tumor effects in colorectal cancer, but upon ligand binding, it promotes cancer cell proliferation." (PMID 39883700, 2025). "In another phase Ib/II study, patients with advanced pancreatic ductal carcinoma, colorectal cancer, or non-small cell lung cancer were treated with a CSF-1R monoclonal antibody plus anti-PD-1 therapy; however, minimal anti-tumor activity was observed." (PMID 40646332, 2025). "Increased macrophage colony-stimulating factor 1 receptor (CSF1R) expression in TAMs within colorectal cancer drives their reprogramming towards the immunosuppressive phenotype." (PMID 40270603, 2025). "Studies found that in colorectal cancer, colony-stimulating factor-1 receptor (CSF1R) inhibitors specifically inhibited the survival of protumor M2 TAMs while having little effect on the growth of anti-tumor M1 TAMs, resulting in an increased M1/M2 ratio." (PMID 39169402, 2024). "CSF1R activation induced the epithelial-mesenchymal transition, invasion, migration, and metastasis of colorectal cancer cells via the STAT3-mediated downregulation of miR-34a." (PMID 37097499, 2023). "The expression of CSF1R in colorectal cancer tissues is significantly higher than that in paracancerous tissues." (PMID 37895197, 2023). "In primary colorectal cancer, the expression levels of CSF1 and CSF1R were associated with poor patient survival." (PMID 37097499, 2023). "Second, we deleted mono/macrophages and found that deletion of macrophages with anti-CSF1R Ab or clodronate liposomes (CL) ablated the inhibitory effect of anti-C5aR1 Ab on MC-38 colorectal cancer growth in parallel with a decrease in the infiltrated CD8+ T cells." (PMID 38331868, 2024). "Because the mechanisms by which CSF-1R promotes cancer development remain under debate, we aimed to clarify whether CSF-1R drives colorectal cancer progression via directly promoting tumor malignancy or facilitating pro-tumor inflammatory environment." (PMID 35444953, 2022). "In a recent study on a mouse model of colorectal cancer, genetic ablation or pharmacological blockade of colony-stimulating factor 1 receptor (CSF1R)+ macrophages resulted in an increase in tumor-infiltrating Treg cells, limiting the antitumor activity of cytotoxic CD8+ T cell." (PMID 36230505, 2022). "A monoclonal antibody targeting CSF-1R depleted TAMs and increased the CD8+/CD4+ T cell ratio, leading to decreased primary tumor burden and decreased metastasis in mouse models of colorectal cancer and fibrosarcoma." (PMID 40646332, 2025). "To further explore the regulatory role of CSF1R in MDSCs in colorectal cancer, we developed a targeted MDSC-specific nanoparticle delivery system for CSF1R siRNA (LNCs@CSF1R siRNA)." (PMID 38992688, 2024). "A deeper investigation of regorafenib’s effects on CSF1R signaling was performed using preclinical in vitro and in vivo studies with syngeneic CT26 and MC38 mouse models of colorectal cancer." (PMID 37013652, 2023).